CXCR3 (C-X-C motif chemokine receptor 3)
Diseases named in the same sentence as CXCR3 in open-access papers (continued):
Sharing a sentence is not in itself a finding about the gene and the disease.
tumor (continued). "This in turn causes the transfer of a large amount of CXCR3+CD8+T and CXCR3+CD4+T cells into the tumors, which take part in anti-tumor activities." (PMID 35095920, 2021). "To explore the difference in the CXCL10/CXCR3 biological axis between normal and tumor tissues, we performed GEPIA database analysis, which showed that the CXCL10 gene was significantly overexpressed in CC." (PMID 34345201, 2021). "Other studies have shown that active CD26 cleaves the chemokine CXCL10 turning it into an antagonist for its cognate CXCR3 receptor, effectively disrupting the chemotaxis that otherwise recruits CXCR3+ effector T-cells to the tumours." (PMID 34016130, 2021). "On the other hand, the ligands of CXCR3, and CXCL14 and CXCL16, cause tumor infiltration by anticancer tumor-infiltrating lymphocytes (TILs) and thus show anticancer properties." (PMID 33467722, 2021). "The multiple context-dependent roles of CXCR3 pose difficulties in studying CXCR3 in cancer using bulk tumor tissue, as one does not only have to consider the type of cell expressing CXCR3, but what isoform is being expressed." (PMID 34440489, 2021). "Recently it has also been shown that at the tumor site TGF b suppresses CXCR3 expression by CD8+ T cells thus enabling tumors to escape CXCL10 induced recruitment to the tumor site." (PMID 34944943, 2021). "It was well known that CD8+ T cells and NK cells can be recruited via the CXCL9–11/CXCR3 axis, resulting in tumor-suppressing with a form of paracrine." (PMID 34321012, 2021). "H&E-stained images of these tumours showed that the CXCR3 inhibitor treatment resulted in less invasive tumours." (PMID 33795809, 2021). "Mice with established tumours were treated with an anti-CXCR3-blocking antibody at the same time as TAC-diet withdrawal." (PMID 33925140, 2021). "A group of researchers demonstrated that therapy using an IL-7 complex, formed with an IL-7R-Fc, induced anti-tumor responses by increasing tumor infiltration of T cells through CXCR3 chemokine signaling." (PMID 34925323, 2021). "Because CXCR3 activation has a role in promoting the anti-tumor response in PD-1 immunotherapy, a better understanding of the ligands that bind CXCR3 variants (CXCR3A, CXCR3B) and competing receptors (CXCR4, CXCR7) is needed." (PMID 33676416, 2021). "In NPC, immunohistochemistry showed the presence of CXCL10-positive neoplastic cells in the majority of tumours, as well as CXCR3-positive lymphocytes in the accompanying stroma." (PMID 34956172, 2021). "Through inhibiting MMPs such as MMP-9, MMST can recruit CXCR3-positive T cells to focus on tumor due to the increased chemokines in the TME, and then exhibit a synergistic effect with chemotherapeutics such as PTX to achieve chemoimmunotherapy." (PMID 34959271, 2021). "On the one hand, CXCR3 binds to its ligand to activate the immune effector and inhibit tumor growth and on the other hand promote tumor growth and metastasis." (PMID 33829065, 2021). "CXCR3 antagonist has been shown to inhibit the implantation and growth of tumor cells in vitro, and inhibit lung metastasis in a vivo model." (PMID 34321012, 2021). "Hepatic stellate cells express CXCR3 and are responsive to IP-10 in the liver microenvironment, while a reciprocal interaction between tumor cells and macrophages at the metastatic site was observed to promote outgrowth." (PMID 34123844, 2021). "Blocking of CXCL10/CXCR3 signaling in vivo shifts macrophage populations to a tumor-promoting (Ym1+, Fizz+, Arg1+) phenotype, increases fibrosis, and mediates progression of lesions, highlighting the importance of this pathway in PDA development." (PMID 34328416, 2021). "CXCR3+ cells were enriched in tumor tissues from CXCL9high patients, which also was the hotspot for CXCR3+ CD3+ cells." (PMID 34539647, 2021).
tumor (continued). "That the bystander memory T cells showed a dependency on CXCR3 for effective tumor migration is consistent with these results and reinforces that CXCR3-mediated T cell trafficking to tumors can occur in an antigen-independent manner." (PMID 34867942, 2021). "Previous studies have demonstrated the orchestration of CXCR3 in the adoptive-transfer setting of effector T cells to tumours, indicating the pivotal role of chemokines in lymphocyte infiltration." (PMID 34527583, 2021). "Blocking CXCR3 with NBI-74330 in tumor-bearing wildtype and Cxcr3ko mice prolonged the median survival of both groups but had no impact on tumor-infiltrating microglia and lymphocytes." (PMID 34203660, 2021). "CD26 inhibition in an immune-competent model of HCC also impaired tumor growth due to increased infiltration of CXCR3+ NK an T cells." (PMID 34503058, 2021). "Akkermansia muciniphila and Faecalibacterium pausnitzii have demonstrated significant benefits in recruiting CCR9+CXCR3+CD4+ T lymphocytes to the tumor microenvironment through the mediation of IL-12." (PMID 33578709, 2021). "Our data suggest that CXCL4 acts on tumour cells via CXCR3 to regulate their migration and invasion." (PMID 33795809, 2021). "The receptor itself, CXCR3 is involved both directly and indirectly in tumor progression by regulating tumor proliferation, migration, invasion, chemotaxis and immunity." (PMID 34123844, 2021). "Collectively, the CXCR3 axis plays vital roles in anti-tumor immunity through expansion and recruitment of Th1 cells, CD8+ T cells, and NK cells." (PMID 34885241, 2021). "CXCL10 is known to drive the infiltration of immune cells into the tumour bed and was previously reported to bind to CXCR3 only." (PMID 33801414, 2021). "Expression of CXCR3 on tumour-infiltrating CD8+ T effector cells also potentiates immune checkpoint inhibition by anti-programmed cell death-1 (PD-L1) in a colorectal cancer model." (PMID 34200333, 2021). "The cytokine TGF-β inhibits mitochondrial metabolism in human NK cells in the context of breast cancer and in CD8+ T cell suppresses CXCR3 expression and tumour homing." (PMID 34090499, 2021). "Both UMAP plot and violin plot demonstrated that tumor associated macrophages were more likely the main source of CXCL10 and its receptor CXCR3 was highly expressed in T cells." (PMID 34276760, 2021). "CXCL10 is known to bind to CXCR3, which is also present on mast cells and it is one of the probable reasons for increased infiltration of these cells into the tumor area." (PMID 33436641, 2021). "It has been reported that CTCs with higher CXCR3 expression can be recruited to the tumor site by ligands, including CXCL9, CXCL10, and CXCL11, which are known as IFNγ-inducible chemokines." (PMID 34539647, 2021). "Induced expression of CXCL10 by using poly-ICLC can also interact with CXCR3 on effector T cells, prompting their infiltration into tumor." (PMID 34771532, 2021). "We identified multiple tumor-immune interactions, for example between CXCR3, CCL5, TNFRSF1B, and VCAM1-expressing malignant T cells and macrophages/fibroblasts positive for CXCL9, CCR1, GRN, and IGTB1, respectively." (PMID 33816243, 2021). "CXCR3 plays a crucial role in tumor microenvironment and CXCR3 over-expression can recruit more TADCs." (PMID 33407095, 2021). "In vivo, we demonstrate the importance of CXCL10/CXCR3 signaling in the maintenance of an inflammatory microenvironment, and that its blockage drives tumor progression." (PMID 34328416, 2021). "This study investigated the concrete mechanisms involving miRNAsand CXCR3 and discovered that miR-34a, the well-known tumor suppressor miRNA,inhibited CXCR3 expression through regulating the phenotypic modulation of VSMCs inIAs." (PMID 33901269, 2021). "CXCL10 is known to play an important role in the infiltration of immune cells into the tumour bed and was previously reported to bind to CXCR3 only." (PMID 33801414, 2021).
tumor (continued). "In the tumor microenvironment, the CXCL9/10/11-CXCR3 signaling pathway is known to primarily promote the chemotactic movement of CXCR3-activated immune cells into the tumor site for antitumor immunity." (PMID 33547412, 2021). "It has been suggested that CXCR3+ regulatory T cells are attracted to the tumor microenvironment as a result of intratumoral CXCL10 secretion." (PMID 34203869, 2021). "Drugs that augmented paracrine CXCL9/10/11 expression and deactivated CXCR3 expression on tumor cells, have shown anti-tumor activity in several tumor models." (PMID 34321012, 2021). "As a part of the normal homeostatic response, CXCR3-harboring immune cells are activated by IFN-γ-inducible chemokines to execute anti-tumor activities." (PMID 34501934, 2021). "In patients with ovarian cancer, IL-17 derived from Th17 cells has been shown to induce the production of CXCL9 and CXCL10 by tumor cells and tumor infiltrated macrophages, which recruits CXCR3-expressing CTLs and NK cells into tumor tissues." (PMID 34885241, 2021). "The combination of PTX and PMX-53 resulted in transcriptional reprogramming of tumour-associated macrophages and subsequent recruitment of CXCR3+ effector and memory CD8+ T cells to significantly reduce tumour burden, when compared to treatment with PTX alone." (PMID 33802004, 2021). "Actually, phosphorylated STAT1 and STAT3 dimer in tumor cytosol can bind to the PD-L1 promoter to induce PD-L1 expression while inhibition of STAT3 activity by STATTIC mitigates the CXCR3 activation-induced PD-L1 expression in tumor cells." (PMID 33407095, 2021). "Two weeks following final paclitaxel administration, the sitagliptin-mediated increase in CD8+/CXCR3+ expression and colocalisation in tumour tissue was restored." (PMID 33513866, 2021). "(E) Patient tumor tissue stained by ISH for Cxcr3 and overlaying immunofluorescence for inflammatory (CD68+,iNOS+) macrophages." (PMID 34328416, 2021). "The traditional concept is that CXCL10/CXCL9 largely produced at the tumor site is associated with directing the migration of CXCR3+ effector CD4+ and mostly effector -cytotoxic CD8+ T cells, and CXCR3+ NK cells to the tumor site." (PMID 34944943, 2021). "The results indicate that IFN-γ plays a direct or indirect role in the recruitment of CD8+CXCR3+ and CD4+CXCR3+ T cell subsets into SCC tumours." (PMID 33925140, 2021). "Many more Th2 cells (CCR4+CD3+CD8-) than Th1 cells (CXCR3+CD3+CD8-) were detected in tumor stroma and in TLS by immunofluorescence." (PMID 34868011, 2021). "Some studies pointed out that CXCR3 promoted tumor proliferation and invasion through autocrine mechanisms, while other studies showed that CXCR3 inhibited tumor growth by promoting the differentiation of immune cells and activating immune cells." (PMID 34221955, 2021). "A current challenge for immunotherapies is increasing immune infiltration of the tumor and exploiting CXCR3 mediated migration is a promising avenue towards improving TAL-dependent immunotherapies." (PMID 34440489, 2021). "This supports the idea that tumour-producing CXCL10 is able to recruit CXCR3+ infiltrating cells, including CD4 T cells, CD8 T cells, and NK cells." (PMID 34956172, 2021). "In contrast, CXCR3-dependent anti-tumor activity has been found in vitro and in vivo and CXCL11 through the CXCR3 can attract CD8+ cytotoxic T cells to inhibit tumor growth." (PMID 33407095, 2021). "CXCL10 is an important pro-inflammatory cytokine and has been reported to mediate the mobilization of tumor-inhibitory CXCR3+ T cells, as well as natural killer cells, into solid cancers." (PMID 34336848, 2021). "The recruitment of NK cells in the inflamed tissues is regulated by the expression of several chemokine receptors, including CXCR3 that binds to the tumor-derived chemokine ligands." (PMID 33732640, 2021). "CXCL9, CXCL10 and CXCL11 are chemoattractant cytokines for anti-tumor leukocytes that express CXCR3, such as effector T cells." (PMID 33446805, 2021).
tumor (continued). "These chemokines can recruit CXCR3-positive T cells to tumor sites, which is an important step of anti-tumor immunity." (PMID 34959271, 2021). "We found that mice treated with bintrafusp alfa and anti-CXCR3 had significantly worse survival (P = 0.0006, n = 10, 13) and increased tumor volume (P < 0.0001 on day 27, n = 10, 13) relative to mice treated with bintrafusp alfa alone." (PMID 34433873, 2021). "Due to the generally low expression of CXCR3 in the tumor and that alternatively spliced gene region is so small, it will be necessary to use specific CXCR3 targeting techniques (such as qPCR or a Western Blot) to fully analyze its splicing." (PMID 34440489, 2021). "In particular, several crucial chemokines and receptors (CXCL9, CXCL10, and CXCR3), which can recruit CD8+ T cells into the tumor microenvironment, were upregulated in the high-risk group." (PMID 34961815, 2021). "Accumulation of CXCR3+ Th1 cells into the tumor microenvironment delays implanted tumors in mice treated with anti-PD-1 antibodies." (PMID 32194569, 2020). "T cells expressing CXCR3 molecules are known to recruit T cells that attack cancer cells in the periphery, and CXCR3 is therefore an important molecule for anti-tumor immunity." (PMID 32977478, 2020). "The CXCL9-11 chemokines are known to bind CXCR3 and are involved in inducing the infiltration of T and NK cells into the tumor as well as tumor suppression." (PMID 32036449, 2020). "The expression levels of CXCR3/4/5/6/7 were negatively correlated with tumor purity (p < 0.05), suggesting that CXCR3/4/5/6/7 was highly expressed in the ccRCC microenvironment." (PMID 33324682, 2020). "Together, these results support the view that CXCR3 plays a role in T cell migration into the tumour tissue in this macaque tumour model." (PMID 32439888, 2020). "Such a role of the CXCR3 chemokine system is consistent with tumor studies in which vigorous anti-tumor activities of CD8+ T cell response by the PD-1 blockade accompanies CXCL9/10 upregulation." (PMID 33584713, 2020). "The results showed that expression levels of Th17 cells were significantly higher in advanced-stage than in early-stage tumor tissues, whereas the levels of CXCR3+CD8+ cells were lower." (PMID 32503584, 2020). "Regorafenib treatment increased the transcription and protein expression of CXCL10—a ligand for CXCR3 expressed on tumor-infiltrating lymphocytes—in murine HCC and in blood of patients with HCC." (PMID 33234602, 2020). "Primed T lymphocytes gain the expression of certain homing molecules (such as CXCR3) on their surface and thus obtain the capability to migrate toward the tumor site." (PMID 32582551, 2020). "Several studies have reported that tumor cells expressing CXCR3 have increased ligand signaling before the onset of metastasis, which enhances the ability to metastasize." (PMID 33195424, 2020). "We further investigated the regulatory effects of CXCL10/CXCR3 on CD8+ T cell migration using supernatants from freshly obtained CRC tumor tissues." (PMID 32503584, 2020). "Contributing mechanisms included CD4+ T cell-mediated induction of CXCL9 and CXCL10 in the tumor microenvironment to attract CXCR3-expressing CD8+ T cells or to confer a specific cytotoxic CD8+ T cell effector program amongst others." (PMID 32610710, 2020). "It has been previously reported that CD8+ T cells that are adoptively transferred into tumor bearing mice, rely on CXCR3 for tumor entry." (PMID 34458892, 2020). "CXCR3 expression levels were also found lower in tumor tissues with advanced-stage compared with early-stage CRC." (PMID 32503584, 2020). "The NK cells that infiltrated into the tumor lesions expressed higher levels of CXC chemokine receptor 3 (CXCR3) (p < 0.05), a molecule reported to be required for NK cell infiltration, than those in peripheral blood." (PMID 32457755, 2020).
tumor (continued). "In another aspect, for the γδ T cells, tumor-intrinsic mTOR inhibition promotes the epidermal recruitment of CXCL10-mediated CXCR3+ γδ T-cell and shows anti-tumor effect." (PMID 32483450, 2020). "TCB treatment strongly induced the secretion of CXCL10 and increased the frequency of intra-tumor CXCR3+ T-cells pointing to the potential role of the CXCL10-CXCR3 pathway as one of the mechanisms for T-cell recruitment to tumors upon TCB treatment." (PMID 33330050, 2020). "Chemokines such as CXCL9 and CXCL10 can orchestrate the migration of effector CXCR3+ immune cells such as Th1 cells into the tumor sites, subsequently shaping both the tumor immunity and therapeutic responses." (PMID 31991604, 2020). "Judicious regorafenib/anti-PD1 combination therapy can inhibit tumor growth and increase survival by normalizing tumor vasculature and increasing intratumoral CXCR3+CD8 T-cell infiltration through elevated CXCL10 expression in HCC cells." (PMID 33234602, 2020). "Cxcl9 and Cxcl10 have been shown to play significant roles in recruiting Cxcr3+ T cells into the tumor and high levels correlate with improved patient survival." (PMID 32641748, 2020). "CXCR3 is usually expressed on the surface of tumor cells, monocytes, dendritic cells, T cells, and NK cells." (PMID 32685487, 2020). "Previous work in cancer immunity has demonstrated that CXCR3 is necessary for trafficking and efficacy of adoptively transferred anti-tumor T cells, as well as mediating tumor regression following anti-PD1 therapy." (PMID 32273499, 2020). "It is also desirable that DC-based immunotherapies are able to enhance the expression of molecules that empower CTL migration towards tumor areas (e.g., CXCR3 and CD103/CD49a) and that promote CTL avidity for MHC-I molecules on malignant cells." (PMID 32075343, 2020). "In particular, CXCR3 was found to be overexpressed in metastatic tumor cells, and drugs targeting CXCR3 decreased tumor cell migration." (PMID 32090168, 2020). "These CD62L+ cells preferentially expressed CXCR3, which allowed them to infiltrate into tumor tissues." (PMID 32845913, 2020). "Generally, it is accepted that CXCL10-based therapies for cancer due to its ability to attract CXCR3+ tumor-infiltrating lymphocytes (TILs) to tumor sites and sites of inflammation." (PMID 32089645, 2020). "CXCR3 and CXCR7 are CXCL11 receptors, and they are highly expressed in PC tissues; high CXCR3 and CXCR7 expression is associated with tumor apoptosis, invasion, and metastasis." (PMID 32341359, 2020). "Our results are consistent with recent meta-analyses, which have shown that higher CXCR3 expression indicates an advanced tumor stage and is correlated with the occurrence of distant metastasis in solid tumors." (PMID 32225066, 2020). "Although it was shown that the expression of CXCR3 on T lymphocytes mediates their migration to the tumor side, the presence of CXCR3 on malignant cells promoted tumor growth and dissemination." (PMID 32225066, 2020). "Previous studies have correlated the accumulation of TILs in tumours with the expression of the chemokine receptor CXCR3 (receptor for CXCL9, CXCL10 and CXCL11)." (PMID 31803974, 2020). "Recent studies have shown that the CXCR3 protein level is often heightened in tumor tissues than that of adjacent tissues." (PMID 32793288, 2020). "Further, the in vivo Cxcr3−/− model indicated that the efficacy of anti-PD1-mediated tumor control is dependent on the intratumoral CXCR3 receptor–ligand interaction." (PMID 32036449, 2020). "Several studies showed that CXCL9 and CXCL10, particularly CXCL10 produced by tumor or host cells can recruit CXCR3+ tumor-infiltrating CD4+ T cells, CD8+ T cells and NK cells that are associated with tumor suppression." (PMID 32547545, 2020). "Meanwhile, CXCL9, CXCL10 and CXCL11, chemokine ligands for CXCR3, were expressed at high levels in the tumours, thus attracting CXCR3+CD8+ T cells." (PMID 32439888, 2020).